TLE6 (TLE family member 6, subcortical maternal complex member)
Description:
Component of the subcortical maternal complex (SCMC), a multiprotein complex that plays a key role in early embryonic development. The SCMC complex is a structural constituent of cytoplasmic lattices, which consist in fibrous structures found in the cytoplasm of oocytes and preimplantation embryos (By similarity). They are required to store maternal proteins critical for embryonic development, such as proteins that control epigenetic reprogramming of the preimplantation embryo, and prevent their degradation or activation (By similarity). Also required for spermatogenesis: regulates spermatogonia proliferation and cell cycle progression, potentially via regulation of cell cycle regulatory genes such as; CEBPB, CEBPA, CSF3, PCNA, and CDK4 (By similarity). Acts as a transcriptional corepressor of NFATC1-mediated gene expression by contributing to PAX6-mediated repression (By similarity). [Isoform 1]: Component of the subcortical maternal complex (SCMC), a multiprotein complex that plays a key role in early embryonic development.
Synonyms: FLJ14009; GRG6; OZEMA15; PREMBL
Tractability: No criterion of Open Targets' tractability assessment is met for any kind of drug.
Gene: Protein-coding gene on chromosome 19 (2,977,538 to 2,995,179, forward strand). Ensembl gene ENSG00000104953.
Subcellular location: Cytoplasm; Nucleus; Cytoplasm (Isoform 1); Cytoplasm (Isoform 2)
Gene Ontology:
Molecular function: protein binding; structural constituent of cytoplasmic lattice; transcription corepressor activity
Biological process: embryonic process involved in female pregnancy; protein storage; actin filament organization; endoplasmic reticulum localization; epigenetic programming in the zygotic pronuclei; establishment of spindle localization; flagellated sperm motility; mitochondrion localization; negative regulation of canonical Wnt signaling pathway; negative regulation of transcription by RNA polymerase II; positive regulation of embryonic development; regulation of cell division; spermatogenesis; developmental process; regulation of DNA-templated transcription
Cellular component: cytoplasm; cytoplasmic lattice; cytosol; protein-containing complex; subcortical maternal complex; cell cortex; nucleus; sperm midpiece; transcription regulator complex
Genetic constraint (gnomAD): Loss-of-function variants: 71 observed, 77.16 expected, observed/expected ratio (o/e) 0.92, 90% interval 0.76 to 1.12. The synonymous counts are far from expectation, so gnomAD's model fits this gene poorly and the ratio says little. Missense variants: 840 observed, 755.15 expected, observed/expected ratio (o/e) 1.11, 90% interval 1.05 to 1.18. Synonymous variants: 366 observed, 295.07 expected, observed/expected ratio (o/e) 1.24, 90% interval 1.14 to 1.35.
Homologues: Orthologues: chimpanzee TLE6 (99% identical), macaque TLE6 (92% identical), mouse Tle6 (43% identical), rat Tle6 (36% identical). Paralogues in human: TLE2 (27% identical), TLE4 (27% identical), TLE3 (26% identical), TLE1 (25% identical), TLE7 (22% identical), TLE5 (3% identical).
Diseases named in the same sentence as TLE6 in open-access papers:
TLE6 is named in the same sentence as 17 diseases in open-access papers, as found by Europe PMC text mining. Sharing a sentence is not in itself a finding about the gene and the disease. The quoted sentences say what the papers report.
Infertility (9 papers, 2015 to 2025). "Pathogenic TLE6 variants are associated with pre-implantation arrest and infertility, but the mutational spectrum and rescue strategies remain incompletely defined." (PMID 41503355, 2025). "Current clinical screening focuses on known loci; 11 TLE6 variant types have been implicated in infertility, but they explain only a fraction of cases." (PMID 41503355, 2025). "Our findings expand the mutational spectrum of PADI6 and TLE6 associated with embryonic developmental arrest and deepen our understanding of the genetic causes of infertility with recurrent ART failure." (PMID 34036456, 2021). "We discovered a novel TLE6 mutation in the infertile woman with recurrent failure of IVF/ICSI attempts." (PMID 34264011, 2021). "In the present study, using WES and bioinformatics analyses, we identified biallelic TLE6 variants in 4 patients from a cohort of 28 infertile women with PEL, accounting for 14.29% of the cohort." (PMID 34178031, 2021). "During the transition from early embryos to two cells in mice, most of the fertilized eggs of Tle6-mutant female mice cannot cleave, causing infertility." (PMID 32823735, 2020). "Furthermore, phenotypes of infertile women harboring biallelic TLE6 variants in this study are similar to the previously reported clinical cases." (PMID 34178031, 2021). "However, the current research has only found that the TLE6 mutation is related to infertility, and the key regulatory mechanism of TLE6 remains to be explored." (PMID 32823735, 2020). "We sought to assess the effect of the TLE6 mutation on binding to SCMC proteins as this may provide a potential mechanism for the observed infertility phenotype." (PMID 26537248, 2015). "In summary, we have identified novel biallelic mutations in TLE6 and NLRP5 in infertile female patients with EDA." (PMID 40225929, 2024). "In this study, we successfully identified four novel mutations in TLE6 and NLRP5 in infertile female patients diagnosed with EDA, both of which encode the SCMC complex." (PMID 40225929, 2024). "Although the function of TLE6 in female germ cells and its role in infertility have been reported, little is known regarding the importance of TLE6 in male germ cells." (PMID 39512902, 2024). "In this study, we identify four novel compound heterozygous mutations in TLE6 and NLRP5, in two infertile female patients experiencing recurrent EDA, using whole-exome sequencing." (PMID 40225929, 2024). "In 2015, a homozygous substitution (c.1529C > A) in TLE6 was verified by whole-exome sequencing in three infertile women." (PMID 36589837, 2022). "In mice, knockout of certain MEGs, namely, Nlrp2, Mater, Padi6, Floped, and Tle6, leads to infertility or subfertility owing to embryonic arrest." (PMID 34178031, 2021). "Mice that are knocked out for Tle6 exhibit complete infertility that is female-specific, which places TLE6 as one of the less than 30 maternal effect genes identified to date in mammals." (PMID 26537248, 2015). "Here we report one female patient with primary infertility for 6 years and had undergone multiple failed in vitro fertilization (IVF)/intracytoplasmic sperm injection (ICSI) cycles due to a splice‐site mutation in TLE6 (NM_001143986.1(TLE6): c.541+1G>A)." (PMID 34264011, 2021). "The infertility phenotype in Tle6 mutants specifically involves the zygote stage and beyond." (PMID 26537248, 2015).
female infertility (6 papers, 2021 to 2024). Diminished or absent ability of a female to achieve conception. "Mutations in TLE6 are related to female infertility caused by developmental arrest and embryonic lethality." (PMID 38673927, 2024). "Our findings identify a novel nonsynonymous variant, c.G1054C:p.G352R, in the TLE6 gene within a consanguineous Iranian family with autosomal-recessive female infertility and broaden the genetic spectrum of TLE6-associated EDA." (PMID 36271123, 2022). "In conclusion, the present study identified novel mutations in the SCMC genes PADI6 and TLE6 and expanded the spectrum of genetic causes of female infertility with recurrent ART failure characterized by embryonic arrest in development." (PMID 34036456, 2021). "Our study extends the genetic spectrum of female infertility caused by variants in TLE6 and further confirms previously reported findings that TLE6 plays an essential role in early embryonic development." (PMID 34178031, 2021). "Our findings add new information on the genetic basis of female infertility and suggest that TLE6 might be a therapeutic target as well as genetic diagnostic marker for recurrent IVF/ICSI failure." (PMID 34264011, 2021). "Several studies have demonstrated that mutations in SCMC‐related genes (TLE6, PADI6, NLRP2, NLRP5, and KHDC3L) cause human female infertility in the form of an exhibition of EEA and fragmentation." (PMID 35946397, 2022). "With the development of massively parallel exon sequencing, the number of diagnosed cases of TLE6‐related female infertility will increase." (PMID 34264011, 2021).
colon cancer (3 papers, 2013 to 2021). "In colon cancer cell, TLE6 interacts with the gastrointestinal tumor suppressor RUNX3, increasing tumor cell proliferation, colony formation, cell migration, and xenograft tumorigenesis." (PMID 34264011, 2021). "In colon cancer cells, the Tle6 gene interacts with the gastrointestinal tumor suppressor RUNX3, increasing tumor cell proliferation, colony formation, cell migration, and xenograft tumorigenesis." (PMID 32823735, 2020). "Tle6 is recurrently overexpressed in human colon cancer and enhances cell proliferation, colony formation, migration, and xenograft tumorigenicity." (PMID 23555558, 2013). "Colon cancer-related genes such as Nek11, Gucy2c, Srp9, Tle6, and Pdgfrl were also overrepresented in the time-course clusters identified by the MNI analysis in the epididymal and subcutaneous fat tissues and gastrocnemius muscle of mice with diet-induced obesity." (PMID 23555558, 2013).
male infertility (2 papers, 2021 to 2024). The inability of the male to effect fertilization of an ovum after a specified period of unprotected intercourse. "While the effects of Tle6 deficiency on males have rarely been reported, they may be related to potential male infertility." (PMID 39512902, 2024). "Furthermore, in our cohort of control women pursuing IVF/ICSI due to male infertility, we also found that a subject harboring a heterozygous missense variant in TLE6 (c.1067T > C, p.L356P) followed a sperm donation ICSI cycle in which 11 MII oocytes were obtained." (PMID 34178031, 2021).
bipolar disorder (1 paper, 2023). A disorder of the brain that causes unusual shifts in mood, energy, activity levels and the ability to carry out day-to-day tasks. "The importance of TLE6 to brain-related disease is supported through its association with bipolar disorder, and mutations in GDAP1 cause inherited peripheral neuropathies." (PMID 37149835, 2023).
sterility (1 paper, 2015). "Consistent with the published phenotype of mouse Tle6 mutants, embryos from female patients who are homozygous for the TLE6 mutation fail to undergo early cleavage, with resulting sterility." (PMID 26537248, 2015).
TLE6 also shares sentences with these, for which no sentence is quoted: cancer (3 papers); tumor (3); Blindness (1); Colorectal Tumors (1); deafness (1); developmental arrest (1); hydatidiform mole (1); lymphocytoma (1); Obesity (1); peripheral neuropathies (1); Usher syndrome type 1C (1).